IL1B (interleukin 1 beta)
Diseases named in the same sentence as IL1B in open-access papers (continued):
Sharing a sentence is not in itself a finding about the gene and the disease.
cancer (continued). "It is important to note that IL-6 and IL-10, TNF-α, and IL-1β have been implied in the generation of the MDSCs, which are commonly found in cancer patients." (PMID 23616009, 2013). "There is a growing area of research asserting that cancer- and cancer-treatment related fatigue is driven by pro-inflammatory cytokines (e.g., IL-6, IL-1β, TNF-α) and inflammatory pathways (e.g., CRP, IL-1RA) as observed using animal and clinical models." (PMID 23959120, 2013). "They demonstrated that the levels of infiltrating Th17 cells and ascites IL-17 are reduced in advanced cancer cases, and that IL-1β stimulates Th17 cells for IL-17 production and recruitment of cytotoxic T cells." (PMID 24213462, 2012). "In this study, we have extensively reviewed literature and performed a meta-analysis based on all eligible case-control published data to evaluate the association between the IL1B+3954 and IL1-RN VNTR polymorphism and cancer susceptibility." (PMID 23049925, 2012). "In the evolution of cancer, pro-inflammatory cytokines such as IL-1β must overcome the anti-inflammatory effects of TGF-β to boost pro-inflammatory responses in epithelial cells." (PMID 22427868, 2012). "In mucosal tissue from inflamed UC, collagen synthesis, pro-MMP-1, TIMP-1, pro-MMP-9 and IL-1β were significantly increased (p<0.03, all comparisons) compared to cancer control tissues." (PMID 23300643, 2012). "While published clinical trials of IL-1β as a therapeutic target in treatment of cancer is limited, a phase I trial showed treatment with recombinant human IL-1β elevated platelet levels in patients with gastrointestinal cancer." (PMID 21765834, 2011). "In contrast, due to IL-1β's cancer-promoting activities, inhibiting IL-1β function represents a promising new avenue for therapeutic intervention." (PMID 21765834, 2011). "We also confirmed here that the intraperitoneal injection of sulfated CCK-8 (10 and 30 μg/kg) resulted in an increase in IL-1β production in cancer-inoculated regions." (PMID 20979661, 2010). "The concentrations of IL-1β in cancer tissues ranged from 0.845 to 757 pg per mg protein, with a mean level of 37.8±80.2 pg per mg protein." (PMID 20823887, 2010). "The possible role of the inflammatory cytokines in the development and spread of cancer cells led us to examine the involvement of leptin in the production of IL-1a, IL-1b, IL-6 and TGF-β1 by human HCC cells." (PMID 20723213, 2010). "The levels of IL-1β protein in the cancer-inoculated regions were then measured by ELISA, which revealed that the administration of sulfated CCK-8 increased the amount of IL-1β protein compared with that of the vehicle-treated control group (p < 0.01)." (PMID 20979661, 2010). "We have identified a novel pain cascade, in which IL-1β production in cancer-inoculated regions induces ephrin B1 gene expression in DRGs and then ephrin B1 enhances the tyrosine phosphorylation of NR2B via Eph B receptor in the spinal cord." (PMID 20979661, 2010). "This pre-clinical study identified a novel pain cascade involving the release of IL-1β from a cancer-inoculated region, induction of ephrin B1 gene expression in DRGs, and subsequent enhancement of tyrosine phosphorylation of NR2B in the spinal cord." (PMID 20979661, 2010). "We found that IL-1β levels were significantly increased in these regions of cancer-induced pain mice compared with normal mice (p < 0.01)." (PMID 20979661, 2010). "The amount of IL-1β protein in the cancer-inoculated region was reduced by 25.8% in the devazepide-treated group compared with vehicle-treated group." (PMID 20979661, 2010). "Accordingly, we consider that the suppression of IL-1β production by Z-360 was critical for its ability to alleviate cancer-induced pain in a previous clinical study." (PMID 20979661, 2010).
cancer (continued). "Devazepide (10 mg/kg) was administered orally once a day from day 7 to 14 after transplantation, and gene expression of ephrin B1 and the Eph B1 receptor in L4-5 DRGs and the amount of IL-1β protein in the cancer-inoculated region were then measured." (PMID 20979661, 2010). "Based on these results, IL-1β is considered to be a critical factor in the development of opioid-resistant pain, such as cancer-induced pain." (PMID 20979661, 2010). "IL1B made in the laboratory is used as a biological response modifier to boost the immune system in cancer therapy." (PMID 20712896, 2010). "The ratio between the concentrations of IL-1β in cancer tissue and normal mucosa (IL-1β Ca/N ratio: cancer tissue IL-1β concentration divided by normal mucosa IL-1β concentration) ranged from 0.86 to 116 with a mean value of 6.75±10.8." (PMID 20823887, 2010). "Here, we examined the effects of devazepide on ephrin B1 gene expression in DRGs and the level of IL-1β in the cancer-inoculated region in the cancer-induced pain model in mice." (PMID 20979661, 2010). "Interleukin-1β (IL-1β) is a major inflammatory cytokine that has diverse effects on the immune system and is considered to be relevant to cancer development, owing to high levels of serum IL-1β and elevated gene expression in cancer patients." (PMID 20979661, 2010). "In this cascade, IL-1β production from cancer-inoculated regions induces the gene expression of ephrin B1 in DRGs, which then ephrin B1 enhances the tyrosine phosphorylation of NR2B via Eph B receptor in the spinal cord, finally leading to pain." (PMID 20979661, 2010). "Z-360 was found to inhibit this pain cascade, suggesting that Z-360 reduces cancer-induced pain through the suppression of IL-1β production in cancer-inoculated regions, which in turn inhibits ephrin B1 gene expression, and tyrosine phosphorylation of NR2B." (PMID 20979661, 2010). "We demonstrated that IL-1β increased in cancer-inoculated regions and induced the expression of the ephrin B1 gene in the periphery of DRGs." (PMID 20979661, 2010). "Here, devazepide (10 mg/kg) reduced the level of IL-1β protein in cancer-inoculated regions, and significantly suppressed the gene expression of ephrin B1 in DRGs to a similar degree as Z-360." (PMID 20979661, 2010). "Studies have documented constitutive IL-1β protein production in human and animal cancer cell lines including sarcomas and ovarian and transitional cell carcinomas." (PMID 17359523, 2007). "Proinflammatory cytokines were significantly overexpressed (interleukin (IL)-1β, IL-6, IL-8 and tumour necrosis factor-α) both at mRNA and protein levels in the cancer specimens compared with mucosa from controls." (PMID 17088911, 2006). "For example it has been shown that vascular endothelial growth factor (VEGF), IL-1β and IL-6 are upregulated in serum of cancer patients and that VEGF and IL-1β can increase Cx43 expression." (PMID 15987459, 2005). "Likewise, in the MDCa@RBC‐Alipo treatment group, significantly elevated levels of serum cytokines such as TNF‐α, IL‐6, and IL1‐β, which play crucial roles in cellular immunity against cancer, were observed." (PMID 40289661, 2025). "While the regulation of IL‐1β in cancer‐related lymphangiogenesis was seldom reported." (PMID 40135589, 2025). "More importantly, EGR146–49, LCN250 and SOCS351 could be upregulated by IL-1α, IL-1β and IL-6 in immune or cancer cells by activating the NF-κB or STAT3 signaling pathway." (PMID 40523992, 2025). "Likewise, vasoinhibin inhibits the action of several proangiogenic factors (VEGF, bFGF, bradykinin, IL-1β) with an impact on angiogenesis-dependent diseases, including cancer." (PMID 40435350, 2025). "This applies when IL-1β is secreted by immune cells and might be even more relevant when the source of IL-1β is the cancer cells themselves." (PMID 39858071, 2025).
cancer (continued). "Future study may focus on the combinatorial application of IL-1β inhibitors in targeted therapy and provides new perspectives for improving cancer treatment efficacy and tackle down resistance from drugs like vemurafenib." (PMID 41145465, 2025). "Regular PA stimulates the release of skeletal muscle-derived IL-6, which inhibits the release of pro-inflammatory factors (TNF-α and IL-1β) and promotes the release of the anti-inflammatory factor IL-10, inducing an anti-inflammatory environment and improving health outcomes in cancer survivors." (PMID 39896788, 2025). "In addition, circulating levels of IL-1β have been found to be increased in patients with CC as well as with other types of cancers including gastroesophageal cancer, squamous cell carcinoma or breast cancer." (PMID 39305371, 2025). "The release of IL-1β can lead to the activation of various signaling pathways that contribute to the sensation of pain, making it a target for therapeutic intervention in managing cancer pain." (PMID 40579593, 2025). "By inhibiting NF-kB activation, SsnB may diminish the expression of its target cytokines, including TNF-α, IL-1β, and IL-6, which are critical for maintaining cancer cell viability and immune evasion." (PMID 40143078, 2025). "Label transfer using the HNSCC myeloid cells as a reference to identify myeloid phenotypes in CRC/ESCC scRNA-Seq datasets showed that IL11 + CAF similarly correlated with IL1B + inflammatory monocytes suggesting the same immunological niche is present in different cancer types." (PMID 39757146, 2025). "This could lead to a feedback loop where IL-1β stimulates the production of chemokines, enhancing the secretion and activity of IL-1β that can activate signaling pathways promoting cancer proliferation and metastasis." (PMID 39858071, 2025). "IL-1β not only leads to the inhibitory effect of cancer cells on CD8+ T cells directly, but also recruits other components of immunosuppressive cells, including M2 phenotype macrophages, into the microenvironment, generating a vicious cycle leading to tumor immune escape." (PMID 40045411, 2025). "Therapeutically, IL-1β is one of the most promising cytokine targets in cancer: ongoing trials will determine whether IL-1β inhibition can reduce metastases or improve survival, especially in combination with other therapies." (PMID 41007766, 2025). "Among these, IL-6 emerged as the most consistently and markedly increased marker, suggesting it may be a central mediator of cancer-induced neuroinflammation, followed by IL-1β and TNF-α." (PMID 41155372, 2025). "Thus, high levels of inflammatory cytokines, such as IL-1β, are common in various cancer types and recognized as potential cancer biomarkers." (PMID 41551149, 2025). "IL‐1β could directly bind to IL‐1R‐1 expressed in HLECs and promoted the tube formation capacities, which suggests a novel mechanism of cancer‐related lymphangiogenesis in OSCC." (PMID 40135589, 2025). "Additionally, 15 other proteins were up-regulated by IL-1β and subsequently down-regulated by CBD, proteins that have been associated with cancer progression and identified as biomarkers of highly aggressive cancer types." (PMID 40429863, 2025). "In conclusion, SOAT1 could promote OSCC malignancy and regulate the activation of NLRP3 inflammasome to increase the rate of lymphangiogenesis and cancer metastasis via IL‐1β/IL‐1R‐1 axis in OSCC." (PMID 40135589, 2025). "While our cytokine array results demonstrate that EMD-CM from cancer cells primarily induces M2 polarization in macrophages, we also observed an increase in cytokines traditionally associated with M1 polarization, such as TNF-α, IL-1β, and IL-6." (PMID 39941817, 2025). "IL1β increases endothelial cell adhesiveness, enabling cancer cells to adhere to vessel walls." (PMID 40100482, 2025).
cancer (continued). "First, we interrogated the expression of NLRP3, CASP1, and IL‐1β in 90 pediatric ALL PDX samples (Pediatric Preclinical Testing Consortium [PPTC] data set) that served as a platform for choosing the most suitable PDX model to study MCC950 effects on cancer." (PMID 40104043, 2025). "Missense mutations were noticed in all genes except CALML3 and IL1B.On the other hand methylation of hub genes were depicted in in which CCR9 and MUC5B were hypermethylated in CESC which can lead to gene silencing and promote metastasis of cancer." (PMID 40653567, 2025). "In other scenarios, IL-1β and IL-18 are known to enhance T cell-mediated anti-cancer immunity." (PMID 40141358, 2025). "On the other hand, downstream targeting of IL-1β and IL-18 could be less selective overall but more effective in suppressing the pro-inflammatory signals that promote cancer progression." (PMID 40141358, 2025). "IL1B, TNF, etc., were associated with inflammation and cancer-related pathways." (PMID 41155650, 2025). "Colchicine mitigates cancer pain by reducing ROS and NO production, as well as IL-1β secretion." (PMID 40717979, 2025). "IL‐1β has been proven a notorious proinflammation cytokine in cancers." (PMID 40135589, 2025). "All these results provide new important insights that could help to understand how CBD counteracts the effects of IL-1β and the restoration of the epithelial phenotype as a possible control of cancer progression." (PMID 40429863, 2025). "Additionally, the UPP1 level is also positively correlated with the levels of TNF-α and IL-1β in most cancer types, consistent with our findings suggesting that both cytokines are required to upregulate UPP1." (PMID 41243973, 2025). "However, in our scRNA-seq analysis, IL1B/IL1R2 were scarcely expressed outside of TANs, including in cancer cells, suggesting that IL1B-mediated cancer progression is likely driven through TANs." (PMID 41228323, 2025). "Moreover, the mRNA levels of IL-1β were greater in the three cancer cell lines than in the other ovarian epithelial cell lines." (PMID 40244135, 2025). "In addition to clinical trials, more preclinical studies are warranted to better understand the functions of IL-1α and IL-1β in regulating different stages of cancer development." (PMID 40562870, 2025). "Researchers demonstrated an association between polymorphisms in the genes encoding IL-1β and IL-6 and cancer-related lack of energy." (PMID 40298695, 2025). "It has also been shown that in diffuse gastric cancer (DGC), IL-1β from mixed polarized macrophages induces the transformation of non-cancerous fibroblasts (NFs) into cancer-associated fibroblast-like (CAF-like) cells." (PMID 40485724, 2025). "We found that compared to CTNNB1 WT carcinomas, samples harboring CTNNB1 mutations showed significantly decreased levels of IL1A (p-value = 0.045), IL1B (p-value = 0.12), and caspase 1 (p-value = 0.037), while demonstrating similar IL1R1 and IL1R2 expression levels." (PMID 41227323, 2025). "Thus, IL-1β has context-specific roles in tumorigenesis; however, the evidence suggests that IL-1β generated by pyroptosing cancer cells promotes antitumor immunity." (PMID 38391959, 2024). "IL-1β is thought to play an important role in cancer invasiveness, progression, and metastasis, and its inhibition could potentially be a therapeutic strategy for certain malignancies." (PMID 39092264, 2024). "We have recently demonstrated that TNBC are uniquely capable of expressing IL1β due to aberrant activation of the Notch developmental signaling pathway, resulting in the recruitment of TAMs to the cancer, a reduction in activated CTLs, and cancer progression." (PMID 39353903, 2024). "Furthermore, cancer-associated symptoms involve TNF-alpha and IL-1β, which are key orchestrators of chemotherapy-related cardiomyopathies (CTRCDs), myocarditis, vasculitis, and cardiac fibrosis." (PMID 39200115, 2024).
cancer (continued). "This supports the hypothesis of a shared inflammatory etiology between PH and various cancer types, particularly through genes such as IL6 and IL1B that are strongly associated with inflammation and immune responses." (PMID 39635438, 2024). "The interleukin 1 (IL-1) family, long recognized for its pleiotropic effects on inflammation, plays a complex, sometimes contradictory role in different stages of cancer development, there are numerous ligands and receptors in this family; however, IL-1α and IL-1β are the two main agonists." (PMID 39201290, 2024). "Two analyzed cytokines, IL-1β and IL-4, are known for their pleiotropic effects in cancer." (PMID 38835768, 2024). "Meanwhile, the destroyed bacteria and cancer cells can activate immune cells (such as macrophages, neutrophils, and dendritic cells), which release inflammatory cytokines (TNF-α and IL-1β) and reduce anti-inflammatory cytokines (IL-10), thereby further enhancing the efficacy of cancer immunotherapy." (PMID 38472176, 2024). "Also, the coculture of adipocytes with cancer cells led to an increased expression of pro-inflammatory factors, including IL-1β, and also showed an altered phenotype." (PMID 39040042, 2024). "Cytotoxic drugs, including doxorubicin, daunorubicin, melphalan, gemcitabine, fluorouracil, cytarabine, methotrexate, paclitaxel, etoposide, vincristine, and cisplatin, can activate inflammasomes and IL-1β-related pathways in cancer cells but also in myeloid cells in the TME." (PMID 38334625, 2024). "Furthermore, our study also discovered that under the induction of SPP1, pro-cancer genes such as Arg1 and Nos2 were upregulated in MDSCs, while anti-cancer genes like IL1b and TNFα were downregulated." (PMID 39066845, 2024). "NLRP3 inflammasome is composed of NLRP3, apoptosis-associated speck-like protein containing CARD (ASC) and effector pro-caspase-1, and can affect the occurrence and development of IBD and even cancer via regulating the maturation, secretion, and pyroptosis of IL-1β and IL-18." (PMID 38650627, 2024). "Hence, we performed an ELISA-like assay to determine if HA was present in malignant ascites and found that HA was present in high concentration relative to LPS and IL-1β, with a mean concentration of 110 ng/mL and max of ~180 ng/mL." (PMID 38796478, 2024). "The contrasting pro- and antitumoral roles of IL-1β are increasingly well recognized in cancer." (PMID 39224600, 2024). "This hypothesis generating observation supports the inflammatory promotion mechanism for lung cancer and could suggest that IL-1β is a molecular cancer prevention target." (PMID 38870403, 2024). "Future investigations could delve into the intricate relationship between IL-1β levels and cancer progression, providing a theoretical basis for the development of drugs modulating NLRP3 inflammasome." (PMID 38317229, 2024). "Moreover, a recent study showed that chemotherapy induces cancer cells to release IL-1β to promote NET formation, which, in turn, activates latent TGFβ secreted by cancer cells and causes chemoresistance." (PMID 38194275, 2024). "Moreover, IL-1R signaling through the expression of inflammatory mediators promotes cancer cell survival and stemness development (both IL-1β and IL-1α reprogram mesenchymal stem cells secrete β-catenin-inducing factors), creating a cancer stem cell niche." (PMID 39201656, 2024). "For instance, UA crystals activate the inflammasome, which induces the expression of pro-carcinogenic factors such as the nuclear factor kappa-light-chain-enhancer of activated B cells (NF-κB) and interleukin 1 beta (IL-1β), promoting cancer cell proliferation and invasion." (PMID 39687737, 2024). "For example, IL-1β promotes EMT in cancer cells, PG production and leukocyte adhesion on endothelial cells, proteinase production and COX-2-mediated angiogenesis in stromal cells, immunosuppression through induced MDSCs, as well as protumor cytokine production, like that of IL-22." (PMID 38539448, 2024).